EDN2 (endothelin 2)
Diseases named in the same sentence as EDN2 in open-access papers:
EDN2 is named in the same sentence as 52 diseases in open-access papers, as found by Europe PMC text mining. Sharing a sentence is not in itself a finding about the gene and the disease. The quoted sentences say what the papers report.
breast carcinoma (10 papers, 2004 to 2023). "Interestingly, high EDN2 expression appears to be associated with both better survival in renal cell carcinoma patients and the promotion of the invasive abilities of breast cancer cells." (PMID 33782686, 2021). "EDN3 expression, in contrast to abundant EDN1 and EDN2 expression, becomes frequently inactivated by promoter methylation in human breast cancer, potentially causing aberrant activation of the ET-axis, which in turn may promote this disease." (PMID 19527488, 2009). "Studies have shown that EDN2 is highly expressed in clear cell renal cell carcinoma, cervical cancer, and breast cancer." (PMID 33782686, 2021). "Likewise, EDN2 was revealed as a novel prognostic marker in various cancers, including prostate cancer and breast cancer." (PMID 37422626, 2023). "On the contrary, transfected with SV2C could significantly inhibit cell migration in both breast cancer cell lines, while the function of EDN2 was slight." (PMID 34513664, 2021). "A role similar to that of EDN1 has been described for EDN2 in human breast cancer." (PMID 19527488, 2009). "We screened out five protein coding genes (EDN2, CLEC3B, SV2C, WT1, and MUC2) significantly corresponding to the overall survival time of patients with breast cancer in the training group." (PMID 34513664, 2021). "Of the five biomarkers, three genes (EDN2, WT1, and MUC2) were upregulated in the breast cancer samples while CLEC3B and SV2C were decreased." (PMID 34513664, 2021). "We extended our analysis to a breast cancer cell line, MDA-231, and observed that BHLHE41 induced IL-11 up-regulation, and BIRC3 and EDN2 down-regulation." (PMID 27384883, 2016). "Because we found that EDN3 expression is frequently lost in breast cancer tissues, we next compared EDN1, EDN2 and EDN3 mRNA expression in breast cell lines in parallel." (PMID 19527488, 2009). "According to the results, EDN2, CLEC3B, SV2C, and WT1 could significantly influence the prognosis of breast cancer patients." (PMID 34513664, 2021). "A recent study demonstrated abundant expression of EDN1 and EDN2 but complete absence of EDN3 expression in a representative set of human breast cancer cell lines." (PMID 19527488, 2009). "Notably, an ET-axis expression pattern similar to that of breast cancer was recently found in cervical cancer; that is, upregulation of EDN1, EDN2, EDNRA and EDNRB expression was accompanied by downregulation of EDN3 expression in cancerous cervix as compared with normal cervical epithelium." (PMID 19527488, 2009). "However, functions of EDN2 in breast cancer had not been reported." (PMID 34513664, 2021).
retinal degeneration (7 papers, 2010 to 2025). Degeneration of the retina. "Among the downregulated genes were Edn2, a known marker of retina degeneration, Gadd45b, a stress response gene, and Igrm1, a gene that positively regulates macroautophagy." (PMID 40643481, 2025). "It is worthwhile to investigate the chronic activation of ER stress/eIF2 signaling in regulating the expression of Gnb3 and Edn2, as well as their downstream interactions in progressive ocular disorders and severe retinal degeneration." (PMID 39503290, 2025). "This anti-apoptotic gene has been shown to be downregulated in different models of retinal degeneration, such as bright light exposure and elimination of endothelin-2." (PMID 20577653, 2010). "Defects in both EDN2 and COL9A2 have been previously associated with retinal degeneration." (PMID 32150541, 2020). "Defects in both EDN2 and COL9A2 have been associated with retinal degeneration." (PMID 32150541, 2020). "Given the elevated expression of Edn2 and Gfap apparent in the retina of Prom1-KO mice, we hypothesized that ET-2, the mature form of the Edn2 product, might induce the GFAP expression apparent in association with retinal degeneration in the Prom1-deficient animals." (PMID 34664634, 2021).
diabetes (6 papers, 2008 to 2025). "In the pericyte and PDFGB-depletion microvasculopathy, we highlight the role of EDN2, a potent vasoactive factor that overrides the effect of homeostatic regulators of angiogenesis and causes vascular alterations in the diabetic retina." (PMID 40591415, 2025). "As blood flow abnormalities are observed with both diabetes and aging, the common upregulation of Edn2 may represent a common causative factor." (PMID 21633715, 2011). "Icam1 and Edn2 are increased with diabetes and show similar magnitude increases in expression with age." (PMID 21633715, 2011). "Thus, RNV combined with diabetes had the most significant effect on circulating Edn2 protein concentrations." (PMID 27482904, 2016). "Diabetes and RNV produced different staining patterns for Edn2 expression in the retina, yet both led to Müller cell reactivity and support the concept of photoreceptor cell stress being induced in Akita, Kimba and Akimba mice." (PMID 27482904, 2016). "While the EDN1 (endothelin 1) alterations have been well described in DR, induction of EDN2 (endothelin 2), a potent vasoconstrictor, and the endothelin receptor EDNRB (endothelin receptor B) have been described after 6 months of diabetes and light injury." (PMID 18554398, 2008). "Similar to the age-related gene expression changes, both Edn2 and Icam1 showed significantly higher expression in rats with diabetes compared to nondiabetic controls." (PMID 21633715, 2011).
glaucoma (6 papers, 2012 to 2023). Increased pressure in the eyeball due to obstruction of the outflow of aqueous humor. "There was a clear upregulation of inflammatory/immune response genes in the retina detectable at the earliest glaucoma time point, including Gfap, Osmr, Fgf2, Edn2, Stat3, and Socs3." (PMID 37762022, 2023). "In fact, adding endothelin 2 to radiation treated DBA/2 J mice (mice that are typically protected from glaucoma) induces glaucoma-like neurodegeneration." (PMID 30670050, 2019). "The monocyte-like cells that enter the eye produce various molecules that are known to be damaging in glaucoma, including endothelin 2 and complement component C1." (PMID 28446179, 2017). "We have shown previously that Endothelin-2 (Edn2), a component of the endothelin system is upregulated in monocytes and microglia-like cells in the retina and optic nerve during glaucoma." (PMID 23209647, 2012).
colon cancer (5 papers, 2014 to 2020). "Similarly, loss of EDN2 or EDN3 in rat colon mucosa indicates their use as early marker for colon cancer." (PMID 32194414, 2020). "Intriguingly, epigenetic inactivation of ET-2 and ET-3 mRNA and protein was found in rat and human colon tumours and cancer cell lines, as a result of hypermethylation of EDN2 and EDN3 genes." (PMID 25131455, 2014). "Thus, in human and rat colon cancer cell lines as well as in human primary colon cancers, there is down-regulation and hyper-methylation of the EDN-2 and EDN-3 genes." (PMID 32194414, 2020). "In a rat model of colonic tumorigenesis, EDN-2 and EDN-3 expression was lost several weeks before the onset of colon cancer." (PMID 32194414, 2020). "In rat and human colon tumors, hypermethylation of EDN2 and EDN3 genes resulted in the epigenetic inactivation of ET-2 and ET-3 mRNA and corresponding protein." (PMID 26956245, 2016). "Moreover, forced re-expression of EDN-2 and EDN-3 in human colon cancer cells led to inhibition of invasion and migration in vitro." (PMID 32194414, 2020). "In a recent study, low to undetectable expression levels of EDN-2 and EDN-3 were found in human and rat colon cancers, but normal levels in matched control tissues." (PMID 32194414, 2020).
Hypertension (3 papers, 2012 to 2020). The presence of chronic increased pressure in the systemic arterial system. "Concordance of rat and human studies supports the hypothesis that Edn2 is a candidate hypertension gene in females." (PMID 22860086, 2012).
diabetic retinopathy (2 papers, 2016 to 2020). "In another study, endothelin-2 was found to inhibit NADPH oxidase, and endothelin-2-injected mice with injured blood-retinal barrier observed in diabetic retinopathy showed increased expressions of AQP4 in the retina." (PMID 32230876, 2020).
high blood pressure (2 papers, 2012 to 2013). "Notably, Edn2 has been associated with human essential hypertension in a Caucasian population of European origin, although specific functional variants have not been elucidated accounting for the susceptibility to high blood pressure." (PMID 22860086, 2012).
melanoma (2 papers, 2003 to 2023). A malignant, usually aggressive tumor composed of atypical, neoplastic melanocytes. "In conclusion, we reported the association of HRGs with patient prognosis in melanoma and screened for novel gene signatures, including FBP1, NDRG1, GPI, IER3, B4GALNT2, BGN, PKP1, and EDN2." (PMID 37422626, 2023).
prostate carcinoma (2 papers, 2020 to 2023). A carcinoma that arises from epithelial cells of the prostate gland. "In this study, we constructed a model using a Cox proportional hazards model based on the expression of eight immune-related genes that were associated with prognosis in prostate cancer: EDNRB, ANGPTL2, TNFSF15, TNFRSF10D, EDN2, BMP2, NLRP14, and PLK1." (PMID 33197890, 2020).
renal carcinoma (2 papers, 2016 to 2026). A carcinoma arising from the epithelium of the renal parenchyma or the renal pelvis. "Similar effects were seen in a distinct renal cancer cell line, 786-0, however, in HK2 cells (normal kidney) SERPINE1 and IL-11 were downregulated along with EDN2, while BIRC3 was upregulated." (PMID 27384883, 2016).
Arthritis (1 paper, 2011). Inflammation of a joint. "Our genome-wide microarray analysis revealed that endothelin-1 (ET-1) and endothelin-2 (ET-2) showed a marked up-regulation in dorsal root ganglia during the acute phase of arthritis." (PMID 21689431, 2011).
endometrial cancer (1 paper, 2023). Primary or metastatic malignant neoplasm involving the endometrium (mucous membrane that lines the endometrial cavity). "In the case of endothelin-2, we did not notice significant changes in its expression in endometrial cancer compared to control." (PMID 36542159, 2023). "EDN1 showed overexpression as endometrial cancer progressed, while changes in EDN2 levels were not statistically significant." (PMID 36542159, 2023).
glioblastoma (1 paper, 2023). The most malignant astrocytic tumor (WHO grade IV). "The tumor propensity of the macrophage membrane and receptor-mediated endocytosis of endothelin-2 peptide could help the nano-delivery system to efficiently cross the Blood Tumor Barrier (BTB) and target Glioblastoma Multiforme (GBM) regions." (PMID 38140108, 2023).
hyperglycaemia (1 paper, 2016). "We assessed the effect of hyperglycaemia on mRNA expression of Edn2 and Ednrb." (PMID 27482904, 2016). "The important difference was that hyperglycaemia in the absence of vascular disease did not lead to upregulation of Edn2, but excess VEGF and the resultant RNV did." (PMID 27482904, 2016). "Hyperglycaemia alone did not affect Edn2 and Ednrb mRNA expression in retinae of Akita mice neither in young mice after only short-term hyperglycaemia nor in mature mice after long-term hyperglycaemia compared to wt littermates." (PMID 27482904, 2016). "There was no increase in Edn2 and Ednrb mRNA expression in young or mature Akita mice, suggesting that VEGF, not hyperglycaemia, was the driving factor in the upregulation of Edn2 activity in retinae of these mice." (PMID 27482904, 2016).
retinal disease (1 paper, 2014). "Another target that is decreased with ASC injection is an inflammatory factor, endothelin 2 (Edn2), which promotes central nervous system remyelination and acts as a macrophage attractant, both of which are characteristic of retinal disease." (PMID 24416262, 2014).
retinitis pigmentosa (1 paper, 2010). Retinitis pigmentosa (RP) is an inherited retinal dystrophy leading to progressive loss of the photoreceptors and retinal pigment epithelium and resulting in blindness usually after several decades. "In the retina, the expression of Edn2 is highly induced in models of retinitis pigmentosa, retinal detachment, and light damage and the increased production of Edn2 is localized to photoreceptors." (PMID 20454693, 2010).
uveal melanoma (1 paper, 2003). A melanoma derived from melanocytes of the uveal tract. "Four candidate tumour markers, Laminin Receptor 1, Endothelin 2, Von Hippel Lindau Binding protein 1 and Cullin 2, have been selected from genes that were differentially expressed in the uveal melanoma cell lines compared to the normal uveal melanocytes." (PMID 14612903, 2003). "An important role in uveal melanoma development is now suggested for Laminin Receptor 1 (LAMR1), Endothelin 2 (ET2), Von Hippel Lindau Binding Protein 1 (VBP1) and Cullin 2 (CUL2) genes, since their expression levels discriminate between two classes of uveal melanoma." (PMID 14612903, 2003).
cancer (16 papers, 2003 to 2024). A tumor composed of atypical neoplastic, often pleomorphic cells that invade other tissues. "Five hypermethylated regions were in genes previously associated with cancer (TRAP1, SLC38A3, CHRM1, EDN2, and PROX1), while six hypomethylated regions were in genes previously associated with cancer (NUMBL, ALDH1B1, FTCD, FASTKD2, FAM96A, and ARHGAP15)." (PMID 36474183, 2022). "It has been reported that the ETA activation by its agonists (endothelin-1, ET1, and endothelin-2, ET2) promotes cancer progression through a network of cellular pathways and interactions with the tumor microenvironment." (PMID 30918259, 2019). "In mammals the EdnrA receptor binds selectively to Edn1 and Edn2, mediates vasoconstriction, and is overexpressed in many cancers)." (PMID 30811380, 2019). "Comparing HCC in the choline deficient model and choline supplemented model, significant methylation differences were seen in 11 genes previously associated with cancer (hypermethylation of TRAP1, SLC38A3, CHRM1, EDN2, and PROX1; hypomethylation of ALDH1B1, FTCD, FASTKD2, FAM96A, and ARHGAP15)." (PMID 36474183, 2022). "For example, endothelin-2 (EDN2) has been investigated in macrophages and cancer cells." (PMID 34098948, 2021). "Contradictory results have been reported for the role of EDN2 in cancer." (PMID 33782686, 2021). "Several factors, including EZH2, SFTPC, IGFBP5, ELN and EDN2, are regulated by NFIB, which have considerate values in the tumour microenvironment, advancing cancer impulsiveness, angiogenesis, migration and spread." (PMID 37845675, 2023). "The regulation of SPHK1 by Runx2 probably potentiates additional aspects of the cancer phenotype, including angiogenesis (a function assisted by the Runx2 targets VEGFA and EDN2) and drug resistance." (PMID 20863401, 2010). "In contrast to the potentially oncogenic role of EDN1 and EDN2, there is still little knowledge about the role of EDN3 in cancer initiation or progression." (PMID 19527488, 2009).
tumor (15 papers, 2003 to 2025). "To date, most reports have focused on the oncogenic potential of EDN1 and EDN2, both of which are overexpressed in various tumour entities." (PMID 19527488, 2009). "Previously, EDN1 and EDN2 were found to be commonly overexpressed in a broad range of human tumour entities." (PMID 19527488, 2009). "The clinical implication supports the view that EDN3, in contrast to EDN1 and EDN2, may act as natural tumour suppressor in the human mammary gland." (PMID 19527488, 2009). "Hypoxic tumor cells secrete chemokines (e.g., CCL2), hypoxia-inducible factors (HIF-1α, HIF-2α), and endothelin-2, which direct macrophage chemotaxis into the tumor core." (PMID 40422235, 2025). "There were also decreases seen in the expression of AR- and AR-V7-regulated genes in RNA extracted from the tumor tissues, though only the decreases in TMPRSS2 and EDN2 were significant." (PMID 37046780, 2023). "Tumor cells and stroma, which make up the hypoxic core of the tumor microenvironment, promote the production of VEGF, CCL2, CCL5, CSF-1, EMAP-II, endothelin-2, SEMA3A, oncostatin M, and eotaxin." (PMID 37056346, 2023). "RNA was extracted from tumor tissues, and qPCR analyses of AR and AR-V7 regulated genes revealed that there were significant decreases in TMPRSS2 and EDN2 expressions in the bicalutamide and α-mangostin groups." (PMID 37046780, 2023).
infection (7 papers, 2016 to 2021). The state of being infected such as from the introduction of a foreign agent such as serum, vaccine, antigenic substance or organism. "The current study expanded on these two studies by identifying 18 SNPs associated with MAP tissue infection through re-sequencing and fine-mapping in both Holstein and Jersey breeds when the region between EDN2 and HIVEP3 was evaluated." (PMID 34026885, 2021). "Moreover, we identified several genes, encoding for proteins such as endothelin 2 that are downregulated in HIBCPP cells specifically following basolateral infection." (PMID 32872518, 2020). "Association of bovine pTB susceptibility with EDN2 was first identified with a GWAS and SNP-based gene-set enrichment analysis for MAP infection detected via tissue infection or fecal shedding by using in 245 US Holsteins." (PMID 32881967, 2020). "We haven’t observed a significant association between the frequencies of both EDN1 and EDN2 genotypes and clinical outcomes, but the rs882345, rs926632 and rs3026575 of EDN3 showed a modest association with hospitalized infection events." (PMID 31167651, 2019). "RT-qPCR analysis demonstrated that infection with both strains of T. cruzi resulted in increased expression of Ccl4 and Edn2 genes compared with control (p = 0.0014 and p = 0.0111, respectively), whereas Gzmd was down-regulated in both infected groups (p = 0.0047)." (PMID 28273076, 2017). "EDN2 encodes a member of the protein family of secretory vasoconstrictive peptides and works as a ligand for the endothelin receptors, initiating an intracellular signaling cascade, which can modulate MAP tissue infection." (PMID 29056729, 2016). "Luciferase reporter assays were performed to confirm the transcriptional activity of EDN2, demonstrating mobility shifts, indicating that one or more variants in the promoter of EDN2 may result in susceptibility to MAP tissue infection in Holstein cattle." (PMID 29056729, 2016). "Interestingly, the gene encoding for endothelin 1 EDN1, a vasoconstrictor, which is usually secreted by endothelial cells, was upregulated by HIBCPP cells under both infectious conditions; EDN2 was differentially expressed solely following basolateral infection." (PMID 32872518, 2020). "Given the roles that EDN2 has in macrophage signaling, intestinal mucosa, intestinal structure, and how important these functions are during MAP infection, the hypothesis that potential causal mutations associated with MAP tissue infection lie near or within the gene is supported." (PMID 34026885, 2021).
EDN2 also shares sentences with these, for which no sentence is quoted: glomerulosclerosis (3 papers); renal failure (3); cervical cancer (2); ischemia (2); Ataxia (1); bacteremia (1); basal cell carcinoma (1); breast tumor (1); chronic kidney disease (1); clear cell renal cell carcinoma (1); endothelial dysfunction (1); epilepsy (1); essential hypertension (1); Ewing sarcoma (1); glioma (1); Hirschsprung disease (1); hyperuricemia (1); ischemia reperfusion injury (1); kidney damage (1); kidney disease (1); lung adenocarcinoma (1); metastatic disease (1); neuroblastoma (1); Obesity (1); ovarian carcinoma (1); pancreatic cancer (1); pancreatic ductal adenocarcinoma (1); renal adenocarcinoma (1); renal cell carcinoma (1); renal dysfunction (1).
A further 1 disease shares a sentence with EDN2 in 1 paper.